MEN1 (menin 1)
Diseases named in the same sentence as MEN1 in open-access papers (continued):
Sharing a sentence is not in itself a finding about the gene and the disease.
tumor (continued). "Most insulinomas are benign (90% of cases); the malignant forms should be suspected when the tumor size exceeds 4 cm and when the tumor arises in the context of MEN1." (PMID 25298880, 2014). "In our experience with MEN1 tumor tissue that was fixed with 3% glutaraldehyde we obtained beautiful tissue morphology but low immunoreactivity." (PMID 25870702, 2014). "Loss of heterozygosity and menin expression was demonstrated in the tumors, consistent with a tumor suppressor role for the Men1 gene." (PMID 25136513, 2014). "In general, all these Men1 heterozygous mouse models correlate closely with the human MEN1 phenotype regarding tumor incidence and spectrum." (PMID 25136513, 2014). "Homozygous Men1 mice are embryonic lethal due to defects in craniofacial development but heterozygous Men1 mice are viable and have been extensively analyzed for tumor formation." (PMID 25136513, 2014). "MEN 1 represents a syndrome inherited as an autosomal dominant trait, the gene responsible for the disease being a tumor suppression gene called MENIN." (PMID 20108468, 2008). "In fact, although the knowledge of the mechanisms of tumour development in patients with MEN1 has grown tremendously, much work lies ahead." (PMID 17014705, 2006). "The results of these studies agree with Knudson's "two hits" model for tumour development and indicated that the MEN1 gene is a putative tumour suppressor gene." (PMID 17014705, 2006). "Whole-exome sequencing (WES) analysis of 28 (2 additional tumors underwent multiplex PCR testing for MEN1) tumors from 17 patients did not reveal any recurrent variants in 2 or more tumors or tumor and germline DNA." (PMID 39946193, 2025). "Frameshift mutation of MEN1 gene was identified in our case, unfortunately we did not further examine menin protein expression of the tumor." (PMID 40994809, 2025). "Delayed recognition of MEN1 can negatively influence patient outcomes, as tumor progression to malignant stages may occur before appropriate intervention, complicating treatment and leading to an unfavorable prognosis." (PMID 41541958, 2025). "The clinical manifestations of MEN1 vary depending on the tumor site and the hormone secreted by the tumor, and MEN1 may be misdiagnosed." (PMID 40421248, 2025). "Although this recommendation is safe for the majority of patients, up to 20% of MEN1 patients might have aggressive NF‐pNETs characterized by rapid tumor growth and/or the development of lymph node and distant metastases." (PMID 40170567, 2025). "Thus, the most commonly mutated genes in sporadic GEP‐NETs are MEN1, death‐domain‐associated protein (DAXX), and ATRX Chromatin Remodeler (ATRX), occurring in 40%, 25%, and 17% of tumours, respectively." (PMID 39579056, 2025). "Raising awareness of such co-occurrences could prompt earlier diagnostic considerations by refining the differential diagnosis in patients with MEN1 presenting with unusual tumor types." (PMID 41155355, 2025). "However, patients with ZES/MEN1, similarly to other MEN1 patients, have a number of special features that affect the management and, in particular, various aspects of tumor localization which in some cases are controversial." (PMID 41463062, 2025). "While MEN1-associated hyperparathyroidism traditionally was described as “primary hyperplasia”, increasing evidence points toward a multi-glandular neoplastic disease rather than a simple hyperplasia of the gland." (PMID 38244045, 2024). "MEN1 acts as a tumor suppressor gene and follows an autosomal dominant inheritance pattern." (PMID 39201946, 2024). "A case study of a patient with MEN1 mosaicism showed that ccfDNA from thymic variants were detected a month before the relapse of TNET, showing that the TNET was growing, and ccfDNA was suggested as a potential early tumor marker." (PMID 38893191, 2024).
tumor (continued). "Notably, the levels of CD68 + CD163-, indicative of M1 macrophages, were higher in the primary MEN1/DAXXmut (PM) group compared to its metastatic (MM) counterpart (p = 0.280 in tumor, p = 0.332 in stroma)." (PMID 38448900, 2024). "Tumor response to SSAs was higher in MEN1-related NETs as compared to the sporadic counterpart." (PMID 37581846, 2024). "Multiple endocrine neoplasia 1 (MEN1) is an autosomal dominant hereditary multiple endocrine neoplasia syndrome due to a germline heterozygous LOF mutations in the MEN1 gene, located on chromosome 11q13.1, which encodes for the 610 amino acid tumor suppressor menin." (PMID 38038882, 2024). "Pituitary adenomas rank as the third most common tumor in MEN1 adults." (PMID 39201946, 2024). "In this study, we reported for the first time the biological importance of MGMT and a new mechanism by which MGMT expression is regulated by MEN1, that is, the loss of MEN1controlled MGMT transcription and tumor chemosensitivity to TMZ via the activation of β‐Catenin." (PMID 39041891, 2024). "It has been hypothesized that inactivation of the MEN1 gene leads to tumor initiation and progression." (PMID 38244045, 2024). "We hypothesised that PAM may act as a tumour suppressor gene like other pituitary tumorigenesis genes such as MEN1 and AIP, with a somatic second-hit involving the wild-type (WT) allele in accordance with the Knudson two-hit hypothesis." (PMID 38075079, 2023). "Tumors of the anterior pituitary tumor occur in about 30 to 40% of MEN1 patients." (PMID 37409236, 2023). "This may be explained by somatic second-hits that are not identifiable within the limits of the genetic testing methodologies used, such that PAM may still act as a tumour suppressor like other genes involved in pituitary tumorigenesis, such as MEN1 and AIP." (PMID 38075079, 2023). "Clinicopathological data of the MEN1-affected family with tumor location, size, and histology." (PMID 37867522, 2023). "Based on the variation of tumor diameter (pNENs < 15 mm in MEN1) in repetitive measurements by EUS, the least significant change (p < 0.05) could be defined as 15%." (PMID 37444604, 2023). "Originally modeled by Knudsons’ “two hit” hypothesis, complete MEN1 inactivation leading to tumor development is thought to require an additive somatic MEN1 mutation in the context of an existing (i.e., inherited) germline defect." (PMID 37492626, 2023). "The deletion of MEN1 profoundly promoted tumor growth for the duration of the observation period." (PMID 37395406, 2023). "MEN1, which codes for the protein menin, is a tumor suppressor in neuroendocrine tissue." (PMID 36782257, 2023). "Therefore, we aimed to elucidate these issues through a histological analysis of tumors and tumor-like lesions in a Japanese family, comprising a father and his two sons, who had MEN1 with Zollinger–Ellison syndrome (ZES)." (PMID 37867522, 2023). "In patients with MEN1-related neoplasia, a MEN4 is likely to be around 3%." (PMID 37761922, 2023). "Notably, BAY-155 and MI-503 decreased MEN1 protein expression in a tumor- and concentration-dependent manner." (PMID 38003662, 2023). "It is conceivable that depletion of MEN1 might increase the sensitivity of the tumor cells to DNA-damaging therapeutics." (PMID 38003662, 2023). "One study compared cumulative methylation indices and gene-specific methylation levels in 56 TSGs in 95 PNETs (61 MEN1 vs 34 sporadic) and reported that overall DNA methylation levels were comparable and that DNA methylation was increased in larger tumours and in metastatic disease." (PMID 37434653, 2023). "Therefore, changes happened in the tumor suppressor genes MEN1 and CDC73, triggering disequilibrium of H3K4 and H3K9 activities." (PMID 35628190, 2022). "When we transplanted those MEN1-IPCs into the immune-deficient NSI mice, they also mimicked the tumorigenesis ability, generating tumors exhibiting critical pathological biomarkers observed in the original tumor from the patients." (PMID 35954231, 2022).
tumor (continued). "However, no change in p27Kip1 expression was observed in PanNET tissue from hTS/Men1+/ΔN3-8 mice when compared with control Men1+/ΔN3-8 tumor tissue (mean staining score = 200 for both hTS/Men1+/ΔN3-8 and Men1+/ΔN3-8 mouse tissue)." (PMID 36048542, 2022). "Furthermore, MEN1-related PanNETs likewise have a high rate of promoter and genome-wide hypermethylation that is considered a distinctive feature of MEN1-related neoplasms." (PMID 36139607, 2022). "This supports the MEN1 role as tumor suppressor gene in endocrine tissues, in line with the Knudson hypothesis, also known as the two-hit hypothesis, according to which tumor suppressor genes require the biallelic inactivation for tumor development." (PMID 35268848, 2022). "We report a novel heterozygous MEN1 frameshift mutation, potentially causing (at least partial) inactivation of menin tumor suppression potential but lacking a genotype–phenotype correlation." (PMID 35287658, 2022). "Moreover, evaluation of the prognostic value of MEN1 expression in the 1643 primary tumor samples has shown that MEN1 expression is independently associated with worse biochemical relapse-free survival (BRFS) and overall survival (OS)." (PMID 34711954, 2022). "Interestingly, contrary to its role as a tumor suppressor, MEN1 functions as an oncogenic partner in aggressive human acute leukemia and in hepatocellular carcinogenesis." (PMID 36230697, 2022). "MEN1-KO xenograft growth in nude mice was also attenuated by leflunomide, while tissue from an MEN1-KO mouse implanted into wild-type mice showed 20/20 with tumours in controls compared with 6/20 in leflunomide-treated mice." (PMID 36694894, 2022). "Whether MEN1 pro-tumor status is prone to abnormal hematologic proliferations is still under debate." (PMID 36428828, 2022). "Moreover, when the status of GLP-1 was examined, it revealed nearly 80% GLP-1 strong positive-cells in the patient original tumor, and this phenomenon was recapitulated in the MEN1-iPSC modeled tumor on NSI mice." (PMID 35954231, 2022). "In vivo, leflunomide treatment delayed tumor growth of MEN1-/- cells implanted in nude mice." (PMID 39034953, 2022). "The association with MEN1 may not purely be coincidental given that LOH was identified in two 11q13 markers in a resected tumor from an MEN1 patient and several publications have documented deletions of the MEN1 gene in apparently sporadic hibernomas." (PMID 36325452, 2022). "Similarly, carcinoma lobules from the same tumor section isolated from Men1–/– (n = 2; 10 lobules) and hTS/Men1–/– (n = 3; 12 lobules) were also scored and compared for Ki-67 expression." (PMID 36048542, 2022). "However, MEN1 patients commonly have concurrent tumours, and it seems that modifications to the NETest are likely to be required to improve its diagnostic use in such patients." (PMID 35900839, 2022). "Somatic MEN1 mutations have been reported in tumor samples from patients with sporadic TNETs, but have not previously been found in tumor samples of MEN1-associated TNETs." (PMID 35696052, 2022). "MEN1 gene variants are distributed throughout the coding region, which has no obvious hot spots and no obvious genotype/phenotype correlation with tumor spectrum or clinical characteristics." (PMID 35255927, 2022). "Germline mutations occur in several known genes (AIP, PRKAR1A, GPR101, GNAS, MEN1, CDKN1B, SDHx, MAX) as well as familial cases with currently unknown genes, while somatic mutations in GNAS are present in up to 40% of tumours." (PMID 33805450, 2021). "No therapeutic intervention is definitively resolutive; given the genetic nature of the syndrome and the asynchronous development of tumors, MEN1 patients have a high prevalence of post-operative tumor recurrences, both in the parathyroids and the gastro-entero-pancreatic tract." (PMID 34298972, 2021). "Additionally, endocrine tumor development was observed in mice with heterozygous MEN1 deletion, supporting the tumor suppressor role of menin." (PMID 34356858, 2021).
tumor (continued). "In our cohort, the PDX1 gene presented hypermethylated CpG sites in the tumours in subgroups T2 and T3 (mutant ATRX/DAXX/MEN1) compared to tumours in the subgroup T1, which are mainly wild-type for those genes and this subgroup was enriched for functional tumours." (PMID 33536587, 2021). "Medical therapies of MEN1 aim to control hormone over-secretion and tumor growth." (PMID 34298972, 2021). "No pathogenic point mutations associated with any genetic syndrome including MEN1 were found in blood, neither pathogenic point mutations in tumor samples." (PMID 34737724, 2021). "T3 tumours harboured mutations in MEN1 and had no major recurrent copy number changes in their genomes except loss or LOH of the chromosome 11." (PMID 33536587, 2021). "miR-cluster-1 included MEN1-mutant tumours with moderate metastatic potential." (PMID 34439335, 2021). "Despite the mutations in the MEN1 gene that commonly predispose tumor development, there are no obvious phenotype–genotype correlations." (PMID 34769484, 2021). "Unfortunately, it is not possible to predict cancer type development, tumor behavior, or risk of metastases based on the MEN1 gene mutation." (PMID 33919851, 2021). "In conclusion, this review provides a general overview of the candidate miRNAs in MEN1 tumor development that could be possible targets for the future development of RNA antagomirs-based strategies to control MEN1 tumorigenesis." (PMID 33066578, 2020). "From this analysis, we found that only a subset of MEN1 germline mutations are found in tumors, suggesting that the mutations likely contribute to clinical pathologies rather than to neoplasia." (PMID 32937789, 2020). "Notably, MEN1 mutations, which are frequently seen in inherited tumor syndromes, relieve repression by PRMT5, enabling oncogenic signaling and tumor growth." (PMID 32743345, 2020). "Identifying such MEN1 modifiers is of particular importance, as it may provide a tool for predicting tumour manifestations in MEN1 patients, as well as providing novel targets for both mono- and combination-drug therapies." (PMID 32348957, 2020). "Among these patients, 257 had sporadic tumor, and 9 patients had MEN1." (PMID 33204258, 2020). "The absence of cumulative effects from Men1 and Rb1 mutations leads to the suggestion that Menin and pRB are in the same molecular pathway of tumor suppression." (PMID 32733644, 2020). "Direct interaction of PRMT5 with the MEN1 tumor suppressor in pancreatic islet tumors reportedly increases repressive sDMAs on H4 (H4R3me2s) and suppresses Gas1, PTCH1 and c-myc expression, thereby limiting oncogenic SHH (sonic hedgehog) signaling in these tumors." (PMID 32743345, 2020). "Authors speculated that miR-24 might promote cell growth and metastasis and inhibit apoptosis of lung cells, by directly targeting MEN1 mRNA, being responsible for both tumor development and malignant progression." (PMID 33066578, 2020). "Collectively, concomitant deletion of Men1 and Rb1 accelerated tumor development in pancreas." (PMID 32733644, 2020). "Genetic testing for MEN1 mutations should be performed in all patients with MEN1-related tumors, and in the young patients even with only one such tumor, despite the supposedly negative family history." (PMID 32847108, 2020). "We believe that this is the first human tumor cell line derived from a classical MEN1 target or cell type (i.e., from parathyroid, pituitary, or endocrine cells of the pancreas) where the MEN1 gene has been stably knocked out, resulting in a complete lack of menin." (PMID 32884006, 2020). "The MEN1 gene prevents uncontrolled cell division and it is considered a tumor suppressor." (PMID 32937789, 2020).
tumor (continued). "In both works, tumor subgroups and mutations in MEN1, DAXX/ATRX, or the mTOR pathway genes did not associate." (PMID 30657883, 2019). "Pathogenic variants may be either inherited or acquired; in both cases, however, development of disease requires loss of heterozygosity consistent with a role for menin, the MEN1 gene product, as a tumor suppressor." (PMID 31737856, 2019). "Furthermore, genetic ablation of JARID1A/RBP2 decreased tumor formation in the pancreatic islets of Men1 (a tumor suppressor)-defective mice and in the pituitary glands of Rb(+/−) mice, thereby improving the survival of these mice." (PMID 31221981, 2019). "MEN1 encodes menin, which is involved in cell division, genome stability, and gene transcription, whereas CDKN1B encodes p27, which prevents cell cycle progression and acts as a tumor suppressor gene." (PMID 30990521, 2019). "The identification of mutations in ATRX/DAXX genes in sporadic NENs, as well as the high burden of mutations scattered throughout the multiple endocrine neoplasia type 1 (MEN-1) gene in both sporadic and inherited syndromes, provided new insights into the molecular biology of tumour development." (PMID 31443481, 2019). "RASSF1A inactivation may alter the cell cycle in both tumor types, whereas hypermethylation of CDKN2A and inhibition of CDKN1B and CDKN2C caused by MEN1 loss are characteristic of PanNETs." (PMID 30657883, 2019). "Of the 31 genetic tumour RCs, the rates were highest for MEN1 at 26 and 9%." (PMID 30407922, 2019). "Nowadays, genetic testing has a well-established role in confirming diagnosis of MEN1, identifying family members of index patients with MEN1 mutation who are at risk to develop tumor manifestation, and reassuring family members without a mutation." (PMID 30254610, 2018). "346G>T; p.Glu116* in exon 2 of MEN1) in two different tumor samples." (PMID 29435419, 2018). "Similar to a number of recent studies, we have demonstrated in this cohort of PanNETs that, in additional to pathologic stage and grade of the tumor, mutations in DAXX, ATRX, and MEN1 are associated with adverse clinical outcome in comparison to those without these mutations." (PMID 30315258, 2018). "There was no gender difference in the occurrence neither of each tumor type nor in the combination of MEN1-associated tumors in all affected patients." (PMID 29036195, 2017). "Actually, the sister began to undergo clinical surveillance of MEN1 with this opportunity, which may allow for early detection of developing a neoplasm in her future." (PMID 28270118, 2017). "This study revealed heterogeneity among tumors in the same patient with MEN1, suggesting that different tumor-specific tumorigenic mechanisms may contribute to the pathogenesis of MEN1 tumors." (PMID 28969599, 2017). "Therefore, we suggest that MEN1 should be considered in patients with these tumours, and a similar approach taken to the patient with GEP NETs." (PMID 28965289, 2017). "Duodenal somatostatin-producing tumours have also been reported in patients with MEN1." (PMID 28965289, 2017). "WES was performed on tumor and constitutional DNA samples from the patient with MEN1." (PMID 28969599, 2017). "Taken as a whole, these observations provide a possible model for MEN1-related tumor development." (PMID 26871472, 2016). "Studies in patients with MEN1-like tumours, but without MEN1 mutations, revealed some to have CDKN1B mutations." (PMID 26320859, 2016). "Finally, we identified Sox-mediated regulation of Wnt/β-catenin signaling as a mechanism contributing to MEN1-related tumor formation." (PMID 26871472, 2016). "This was seen in both human MEN1 tumor tissues and in two different Men1 KO mouse models." (PMID 26871472, 2016). "In tumour models this is of particular importance as often patients carry a heterozygous mutation but require a second hit to cause loss of heterozygosity (LOH), and the development of a tumour, for example in patients with MEN1." (PMID 26320859, 2016).